IGF2 (insulin like growth factor 2)
Diseases named in the same sentence as IGF2 in open-access papers (continued):
Sharing a sentence is not in itself a finding about the gene and the disease.
Hypoglycemia (continued). "Because IGF2 is less effective than insulin in stimulating glucose uptake, even a large dose of intranasal IGF2 would be unlikely to cause hypoglycemia." (PMID 36971212, 2023). "The observed amelioration of hypoglycemia by MOE in EAC mice may be attributed to the reduction in IGF2 production." (PMID 38098043, 2023). "Therefore, for patients with breast PTs with severe hypoglycemia in whom high levels of IGF-2 are detected in tumor cells or serum, the diagnosis of NICTH can be considered." (PMID 33841338, 2021). "Blood work during symptomatic hypoglycemia was consistent with an IGF-2-producing tumor." (PMID 34104499, 2021). "The second mechanism, termed non-islet cell tumor hypoglycemia (NICTH), involves the formation of a certain high molecular weight form of insulin like growth factor 2 (IGF-2), which abnormally binds to insulin receptors in the tissues, leads to increased glucose utilization, and causes hypoglycemia." (PMID 33841338, 2021). "In addition, another study had found that IGF-2 played a certain role in the diagnosis of the large breast borderline PTs with hypoglycemia." (PMID 33841338, 2021). "Non-islet cell tumor hypoglycemia (NICTH) is a rare paraneoplastic syndrome that secretes incompletely processed high molecular weight insulin growth factor 2 (big-IGF2), which results in stimulation of the insulin receptor and subsequently induces hypoglycemia." (PMID 32393233, 2020). "Ectopic IGF-2 production is a rare but often fatal complication of many cancers, and should be considered on the differential diagnosis in patients with malignancy and unexplained hypoglycemia." (PMID 29340167, 2018). "Whether IGF-2 level should be routinely measured in the evaluation of hypoglycemia depends on the prevalence of the condition." (PMID 24934576, 2014). "Accumulating literature provides a firm basis for routine IGF-2 laboratory evaluation in patients presenting with spontaneous hypoglycemia with no readily apparent cause." (PMID 24934576, 2014). "SFT in other locations has been demonstrated to cause hypoglycemia secondary to IGF-2 production, but this has not been demonstrated in the hypopharynx." (PMID 24027649, 2013). "The plasma level of IGF-2 was not measured in the current case, and the exact mechanism causing hypoglycemia was not determined." (PMID 18485198, 2008). "However, not all big-IGF2-producing SFTs result in hypoglycemia, implying the involvement of additional pathogenic factors." (PMID 41858356, 2026). "However, IGF-2-mediated hypoglycemia often recurs despite optimal nutritional intake." (PMID 41333493, 2025). "Thus, therapeutic doses of subcutaneous IGF2 sufficient to confer neural benefits are not expected to cause hypoglycemia." (PMID 36971212, 2023). "However, excessive expression of IGF2 can result in the occurrence of hypoglycemia." (PMID 37152930, 2023). "The occurrence of hypoglycemia in dogs with hepatic neoplasia is suggested to be secondary to the increased generation of insulin-like growth factor 2 (IGF-2), a normal product of hepatic metabolism that may be secreted in excess with increased tissue (tumor) volume." (PMID 36136704, 2022). "Preoperative hypoglycemia may be affected by IGF-2 produced by PTs." (PMID 33841338, 2021). "A high-molecular-weight form of insulin-like growth factor-2 (IGF-2), known as “big” IGF-2, is occasionally produced in various tumor types regardless of whether the origin is mesenchymal or epithelial, and can lead to hypoglycemia through insulin receptor (IR) signaling." (PMID 32993631, 2020). "In spite of structural homology with insulin, normal levels of IGF-2 do not cause hypoglycemia." (PMID 24934576, 2014). "Serum samples were drawn for IGF-2, IGF-1, IGF binding protein 3 (IGFBP-3), insulin, proinsulin, and C-peptide prior to hypoglycemia correction." (PMID 40270996, 2025).
Hypoglycemia (continued). "Serum samples drawn prior to hypoglycemia correction revealed an elevated IGF-2:IGF-1 ratio of 60.7 (normal <10) with low paired C-peptide and insulin, consistent with an IGF-2–secreting tumor." (PMID 40270996, 2025). "Nonislet cell tumor hypoglycemia (NICTH) is a rare paraneoplastic phenomenon in which a tumor induces hypoglycemia through overproduction of insulin-like growth factor 2 (IGF-2) and its precursor molecule pro-IGF2." (PMID 39372824, 2024). "As such, we recommend interpreting the IGF-2/IGF-1 ratio with caution and as part of a holistic evaluation of a patient with unexplained fasting hypoglycemia." (PMID 38432069, 2024). "In NICTH, big IGF-2 forms a complex that is biologically active and saturates the insulin and IGF receptors, resulting in refractory hypoglycemia." (PMID 38405103, 2024). "Intravenously applied ERT using IGF2.GAA has been tested in a clinical trial with adult-onset Pompe patients, and this revealed a dose-dependent transient induction of hypoglycemia starting at a dose of 10 mg/kg during and/or within 2 h of the end of infusion." (PMID 36284764, 2022). "Subsequent measurement of the serum IGF2:IGF1 ratio was elevated at 22.3 and consistent with IGF-2 mediated hypoglycemia and imaging studies demonstrated a pelvic mass." (PMID 36303203, 2022). "It has been estimated that 4–6% of SFT patients develop hypoglycemia due to circulating big IGF-2, and the mean time elapsed from tumor detection until the onset of big IGF-2-induced hypoglycemia is reportedly 8.5 ± 1.9 months." (PMID 32993631, 2020). "In the differential diagnosis in those presenting with hypoglycemia, it was necessary to exclude insulinomas, adrenal insufficiency, hypothyroidism and IGF1, IGF2 producing tumors." (PMID 32813762, 2020). "A high-molecular-weight form of insulin-like growth factor-2 (IGF-2), known as “big” IGF-2, is occasionally produced by various tumor types, leading to hypoglycemia." (PMID 32993631, 2020). "We should keep in mind that even a long-inactive SFT can undergo transformation to produce big IGF-2, which then acts on both insulin and IGF-1 receptors, possibly leading to both hypoglycemia and the development/growth of another tumor, respectively." (PMID 32993631, 2020). "Tumor-induced hypoglycemia (TIH) associated with hepatocellular carcinoma (HCC) results from tumor production of insulin-like growth factor 2 (IGF-2), resulting in recurrent hypoglycemia." (PMID 31737377, 2019). "Unlike insulin-mediated hypoglycemia, IGF-2-induced hypoglycemia is characterized by low insulin, low C-peptide, low β-hydroxybutyrate, and variable cortisol levels." (PMID 41333493, 2025). "Non-islet cell tumor hypoglycemia (NICTH) is a rare paraneoplastic phenomenon of tumor insulin-like growth factor (IGF)-2 hypersecretion." (PMID 41179270, 2025). "Although NICTH is typically diagnosed with an IGF-2/IGF-1 ratio greater than 10, a ratio below this threshold does not exclude the diagnosis, particularly in the presence of fasting hypoglycemia with suppressed insulin and ketones, findings consistent with IGF-2 mediated effects." (PMID 40727482, 2025). "Here, we present a rare case of a presumed IGF-2-mediated non-diabetic hypoglycemia in an elderly male." (PMID 41333493, 2025). "On the other hand, all IGF2 transgenic mice displaying more than 30 times the IGF-II levels compared to non-transgenic control animals did constantly display reduced blood glucose levels and symptoms of hypoglycemia." (PMID 38255147, 2023). "Dysregulation of IGF-2 proteoform composition with increased concentration of long proteoforms is typical in non-islet cell tumor induced hypoglycemia." (PMID 33673334, 2021). "DPS has been characterized as a non-islet cell tumor hypoglycemia due to the ectopic secretion of insulin-like growth factor 2 (IGF-2), a pattern seen in fewer than 5% of cases of SFT." (PMID 32494533, 2020).
Hypoglycemia (continued). "Non-islet cell hypoglycemia (NICH) is hypoglycemia due to the overproduction of insulin-like growth factor-2 (IGF-2) and its precursors which can activate the insulin receptor." (PMID 31156561, 2019). "Accumulating literature supports screening for IGF-2 in non-diabetic individuals who present with hypoglycemia along with suppressed insulin and c-peptide levels." (PMID 24934576, 2014). "Non-islet-cell tumour hypoglycaemia also occurs, most commonly due to glucose utilisation or excess insulin-like growth factor 2 (IGF2) secretion." (PMID 24683485, 2014). "In a series of 78 cases of non-islet-cell tumour, hypoglycemia (NICTH) due to IGF-2 production, hepatocellular carcinoma and gastric carcinoma were the common causes." (PMID 24741994, 2014). "Therefore, in clinical settings, circulating IGF-2 is only measured when there is a suspicion of non-islet cell tumor-induced hypoglycemia." (PMID 40522948, 2025). "Therefore, when encountering a malignant SFT with diffuse and strong IGF2 expression and without hypoglycemia, other lesions promoting hyperglycemia need to be ruled out." (PMID 38982409, 2024). "Secondly, individual variability in receptor sensitivity to IGF‐2 might influence the clinical manifestation of hypoglycaemia, independent of the IGF‐2:IGF‐1 ratio." (PMID 38411039, 2024). "However, non-islet cell tumors can also trigger hypoglycemia by releasing insulin-like growth factor 2 (IGF-II) or its precursor." (PMID 38283730, 2024). "Non-islet cell tumor producing insulin-like growth factor 2 involves hypoglycemia." (PMID 32025979, 2019). "Thus, the diagnosis of a non-islet cell tumor-induced hypoglycemia (NICTH) was established on the basis of the hypoinsulinemic hypoglycemia, the MSFT history, the presence of an immature form of IGF2, and the exclusion of any other hypoglycemic causes." (PMID 24891941, 2014). "Recurrent fasting hypoglycemia in the setting of a malignancy should raise suspicion of non-islet cell tumour hypoglycemia (NICTH), which is typically mediated by IGF-2." (PMID 38432069, 2024). "In the absence of IGF2 assays, low serum insulin in combination with low IGF1 levels at the time of hypoglycemia is helpful in making the diagnosis of NICTH." (PMID 24616774, 2013). "The precise mechanism of hypoglycemia in SRS and likewise IGF2 dysfunction is not clear to date, but several factors are discussed: IGF2 presumably is able to bind to both IGF1 and IGF2 receptors as well as the insulin receptor and interacts with IGFBP3, possibly influencing glucose homeostasis." (PMID 33922271, 2021).
Obesity (110 papers, 2007 to 2025). Accumulation of substantial excess body fat. "With regards to obesity, maternal smoking has been associated with hypermethylation of the insulin-like growth factor 2 (IGF2) promoter and brain-derived neurotrophic factor (BDNF) gene involved in growth and satiety regulation." (PMID 40806516, 2025). "Studies have found that the methylation level of IGF2 after birth is related to obesity, and a reduction in IGF2 methylation will increase the risk of metabolic diseases, and this process is affected by methylation." (PMID 39202427, 2024). "The E-domain of the IGF2 protein, also known as preptin has been further associated with obesity and T2DM." (PMID 36982475, 2023). "The methylation of IGF2 at H19 is associated with an increased risk of early-onset obesity in children and higher circulating levels of the protein encoded by IGF2 in adults." (PMID 36012526, 2022). "While inconsistent with truncated growth, elevated igf1/igf2 levels have been linked to obesity and attenuation of lipolysis." (PMID 34673019, 2021). "Human studies of the APAI polymorphism in the IGF2 gene have shown that the APAI A allele is associated with higher serum IGF-II (s-IGF-II) and less obesity as well as a prolonged life expectancy." (PMID 34072372, 2021). "The degree of IGF-2 methylation at birth has previously been linked to the development of childhood overweight and obesity." (PMID 33681100, 2021). "Though several studies have previously revealed an association between IGF2 (rs680) and obesity, BMI or plasma glucose levels, these results were previously controversial, and the association between rs680 and the risk of MetS was still unclear." (PMID 34093434, 2021). "A similar association between IGF2 hypomethylation and paternal obesity was previously reported in neonates enrolled in the Newborn Epigenetics Study cohort." (PMID 31246962, 2019). "At the age of 58 years, these patients showed reduced methylation of the imprinted gene IGF2 (Insulin-like growth factor 2) and a higher risk of obesity or glucose intolerance." (PMID 31921275, 2019). "Hypomethylation of IGF2 and increased IGF2 protein have been associated with paternal obesity, as well as increased offspring obesity risk." (PMID 30246009, 2018). "IGF2 is documented to be linked to growth retardation, overgrowth, obesity, polycystic ovary syndrome, and cancer." (PMID 28848601, 2017). "Prenatal exposure to famine during the Dutch hunger winter of 1944 is associated with obesity with less DNA methylation of the imprinted insulin-like growth factor 2 (IGF2) gene in exposed offspring relative to their unexposed siblings." (PMID 27888796, 2016). "Our findings suggest that down-regulation of Peg3 and Igf2 in adipocytes contributes to diet-induced obesity and the symptoms associated with obesity." (PMID 24416415, 2014). "In adult humans, lower circulating IGF2 levels have been associated with an increased risk of weight gain and obesity." (PMID 24416415, 2014). "We show that one of the measurable lifestyle parameters, obesity of the father, is associated with hypomethylation at the IGF2 DMR in the offspring." (PMID 23388414, 2013). "In this study, our aim was to determine associations between preconceptional obesity and DNA methylation profiles in the offspring, particularly at the differentially methylated regions (DMRs) of the imprinted Insulin-like Growth Factor 2 (IGF2) gene." (PMID 23388414, 2013). "In brief, without adjusting for potential confounders we detected significantly lower methylation at the IGF2 DMR associated with paternal obesity, and significantly higher methylation at the H19 DMR when the mother was obese." (PMID 23388414, 2013). "In adult humans, lower circulating IGF2 levels have been associated with increased risk of weight gain and obesity." (PMID 23148549, 2012). "No other significant association between the alleles or genotypes of insulin -23Hph and IGF2 Apa and diabetes or obesity was identified." (PMID 21637566, 2010).
Obesity (continued). "As a consequence, several functional polymorphisms from the insulin – IGF2 region have been frequently implicated with diabetes and/or obesity in association or linkage based studies." (PMID 21637566, 2010). "For example, body weight is affected by several polymorphisms in the Igf2 gene, and low circulating IGF2 concentrations are associated with weight gain and obesity." (PMID 19835573, 2009). "Importantly, circulating IGF2 levels are often elevated in obesity but can be reduced with weight loss, reinforcing its metabolic role." (PMID 40566344, 2025). "In humans conceived during the Dutch Hunger Winter, an increased risk for obesity was observed and methylation differences in whole blood are found related to genes involved in growth and metabolism including lower methylation of insulin-like growth factor 2 (IGF2) gene." (PMID 38484284, 2024). "IGF2 is a well-known growth factor involved in cell proliferation, development and cell growth and its overexpression has been linked to multiple metabolic diseases including obesity and metabolic bone disease." (PMID 38470198, 2024). "Therefore, the placental expression of its receptor, IGF2R, should be relevant to the biological function of IGF2 and its involvement in the risk of developing obesity in the offspring of women with obesity." (PMID 37408866, 2023). "However, in the NEST cohort (Newborn Epigenetics Study), genetic analysis of IGF2 expression showed that paternal obesity is associated with IGF2 hypomethylation in newborns." (PMID 35626807, 2022). "Our in vivo data confirms reduced IGF2 levels in obese mice and our in vitro work revealed the strong clinical application for deploying IGF2 in fertility clinics for ART purposes to increase the pregnancy outcomes by reducing meiotic defects associated with obesity." (PMID 35836183, 2022). "The paternal transmission of obesity in mice was correlated with the expression of the imprinted genes for IGF2, which might contribute to the symptoms associated with obesity." (PMID 35626807, 2022). "Studies have found that lower Igf2 concentration is associated with weight gain and obesity." (PMID 33746902, 2021). "Studies also show paternal gene imprinting of alleles related to body fat accumulation, Igf2 and Peg3, to be decreased in obesity-resistance mice compared to obesity-prone mice, suggesting a likelihood of paternal gene transmission in offspring resulting in diet-induced obesity." (PMID 33324346, 2020). "Furthermore, IGF2/H19 DMR methylation changes have also been associated with paternal obesity or the risk of overweight, diabetes or some types of cancer in early life." (PMID 31615571, 2019). "IGF2 overexpression in adult mice liver would decrease fat body mass, and low levels of circulating IGF2 concentrations were associated with weight gain and obesity in humans." (PMID 31208008, 2019). "Global deletion of the mRNA-binding protein insulin-like growth factor 2 mRNA-binding protein 2 (IGF2BP2 or IMP2) in mice causes resistance to obesity and fatty liver induced by a high-fat diet (HFD), whereas liver-specific IMP2 overexpression results in steatosis." (PMID 31209109, 2019). "In the Dutch Famine cohort, offspring exposed to maternal famine in early gestation had reduced methylation at the IGF-2 differentially methylated region (DMR), an imprinted region of differential methylation within the IGF-2 gene, and were associated with obesity in later life." (PMID 28786951, 2017). "Insulin-like growth factor 2 (Igf2), which is one of the best known epigenetically imprinted genes, and a key intra-ovarian regulator of follicular development and steroidogenesis, is associated with greater body weight, obesity, and polycystic ovary syndrome." (PMID 28417351, 2017). "Interestingly, genetic variants of the IGF2 gene were correlated to obesity, obesity-associated hypertension, and intramuscular fat." (PMID 27199763, 2016).